JAK1 (Janus kinase 1)
Diseases named in the same sentence as JAK1 in open-access papers (continued):
Sharing a sentence is not in itself a finding about the gene and the disease.
Cerebral ischemia (5 papers, 2019 to 2025). Restriction of arterial blood supply to the brain associated with insufficient oxygenation to support the metabolic requirements of the tissue. "The JAK1/STAT pathway is an important pathway, regulating apoptosis induced by cerebral ischemia and ameliorating neuronal damage caused by cerebral ischemia." (PMID 38155906, 2023). "Previously, it was demonstrated that Jak1 and Stat3 mediated pathway is activated in astrocytes following a transient focal cerebral ischemia (50-min occlusion)." (PMID 31733648, 2019). "Moreover, treadmill training could relieve cerebral ischemia‐reperfusion injury by facilitating M2 microglia activation through IL‐4 upregulation mediated by the JAK1/STAT6 pathway." (PMID 37143406, 2023).
cutaneous melanoma (5 papers, 2018 to 2023). A primary melanoma arising from atypical melanocytes in the skin. "While resistance mechanisms to immunotherapy in cutaneous melanoma have been uncovered, including alterations in JAK1/2, B2M, or STK11, a switch of oncogenic drivers under immunotherapy has not yet been observed." (PMID 34072863, 2021). "JAK1, JAK2 and STAT3 genotypes and alleles in 248 cutaneous melanoma patients and 274 controls." (PMID 35982955, 2022). "JAK1, JAK2, and STAT3 significant combined genotypes in 248 cutaneous melanoma patients and 274 controls." (PMID 35982955, 2022). "The second example is a selective JAK1 and JAK2 inhibitor ruxolitinib and the skin melanoma cell line A375 with a GRmax value of − 0.25." (PMID 36434556, 2022). "JAK1, JAK2, and STAT3 haplotypes in 248 cutaneous melanoma patients and 274 controls." (PMID 35982955, 2022).
Cutaneous T-Cell Lymphoma (5 papers, 2017 to 2026). "Acquired mutations were recently described in cutaneous T-cell lymphomas for the JAK1, JAK3, STAT3, and STAT5B genes of the JAK-STAT pathway." (PMID 29262599, 2017). "JAK1 may have a pathogenic role, particularly in the early stage of cutaneous T-cell lymphoma." (PMID 41861759, 2026). "Deregulated JAK/STAT signaling due to JAK1 and JAK3 somatic mutations has also been observed in Cutaneous T-Cell Lymphoma (CTCL), supporting malignant proliferation." (PMID 41438753, 2025). "Deregulated JAK/STAT signaling due to JAK1 and JAK3 somatic mutations has been observed in Cutaneous T-Cell Lymphoma (CTCL)." (PMID 34055801, 2021).
Ewing sarcoma (5 papers, 2014 to 2024). A small round cell tumor that lacks morphologic, immunohistochemical, and electron microscopic evidence of neuroectodermal differentiation. "Our identified chemotherapy-induced JAK1/STAT6/GAS6/TAM signaling contribution to chemoresistance in cancer warrants study beyond Ewing sarcoma." (PMID 38906855, 2024). "We applied the filter method to Ewing sarcoma and discovered multimodal expression of an important druggable gene, JAK1." (PMID 32275708, 2020). "Using phospho-profiling, genetic, and biochemical approaches, our studies unravel a chemotherapy-induced mechanism for JAK1/STAT6/GAS6-mediated autocrine or paracrine signaling contributing to Ewing sarcoma chemoresistance, by activating TAM kinases and subsequent downstream Akt and ERK signaling." (PMID 38906855, 2024). "However, due to the small number of patients in this study, we cannot conclude if increased JAK1/STAT6 expression contributes to Ewing sarcoma chemoresistance." (PMID 38906855, 2024). "Whether JAK1 or TAM kinase inhibition similarly sensitizes Ewing sarcoma to radiation which also relies on generating DNA damage remains to be determined." (PMID 38906855, 2024). "Importantly, pharmacological inhibition of either JAK1 by filgotinib or TAM kinases by UNC2025 sensitizes Ewing sarcoma to chemotherapy in vitro and in vivo." (PMID 38906855, 2024). "Overexpression analysis using the Ewing sarcoma JAK1 expression distribution may identify JAK1 as an actionable lead, but further investigation into the effect of inhibiting off-target JAK1 expression in mast cells is needed." (PMID 32275708, 2020). "We find various kinases within this signaling can be targeted, including JAK1 and TAM by small molecule inhibitors to sensitize Ewing sarcoma to chemotherapy." (PMID 38906855, 2024). "Our study reveals the chemo/JAK1/STAT6 signaling also promotes GAS6 transcription and secretion in Ewing sarcoma." (PMID 38906855, 2024). "Selective IFN-β-induced activation of Jak1 and higher STAT-1 phosphorylation upon IFN-β vs. IFN-α treatment were observed in both human myocardial fibroblasts and vascular endothelial cells, and a superior antiproliferative effect of IFN-β over IFN-α was shown in Ewing’s sarcoma cells in vitro." (PMID 24472094, 2014).
Hepatitis (5 papers, 2021 to 2025). Inflammation of the liver. "Together, these findings suggest that JAK1 polymorphisms may be linked to both key genetic mutations and hepatitis‐related HCC." (PMID 40344393, 2025). "IFN‐γ was demonstrated to upregulate the expression of many autophagy‐related proteins such as double‐stranded RNA‐dependent protein kinase (Pkr), Atg7, LC3‐II, p62 through the Janus Kinase 1(JAK1)/STAT1 signaling pathway in Con A‐induced hepatitis." (PMID 35263512, 2022). "In summary, we report an individual with a heterozygous gain-of-function mutation in JAK1, with consequent hyperactivation of JAK-STAT signaling pathways leading to a syndrome of multi-organ inflammation: AiKD with hepatitis and autism." (PMID 35046931, 2021). "Furthermore, 80% of JAK1 polymorphisms were found in hepatitis‐related HCC cases, indicating that hepatitis infection may contribute to the occurrence of JAK1 polymorphisms." (PMID 40344393, 2025). "By primarily activating the anti-inflammatory cytokine (IL-10) mediated JAK1/STAT3 signaling pathway, PAE also effectively reduced oxidative stress-induced liver inflammation while also reducing liver damage, as evidenced by the reductions in serum AST and ALT." (PMID 36139880, 2022).
Hodgkins lymphoma (5 papers, 2010 to 2023). A heterogeneous group of malignant lymphoid neoplasms of B-cell origin characterized histologically by the presence of Hodgkin and Reed-Sternberg (HRS) cells in the vast majority of cases. "For example, when brentuximab vedotin is combined with a JAK1/2 inhibitor, ruxolitinib, it shows enhanced efficacy against Hodgkin lymphoma." (PMID 37120688, 2023). "In Hodgkin lymphoma cells, inhibition of HSP90 led to loss of JAK1, JAK3, and Tyk2, and constitutive pY of STAT1, 3, 5, and 6 was ablated." (PMID 32272626, 2020). "The Hodgkin lymphoma cell line HDLM-2 has been demonstrated to show constitutive phosphorylation of JAK1 and JAK2, and STAT1, STAT3, STAT5 and STAT6." (PMID 26131691, 2015). "Hodgkin's lymphoma L540 cells had high levels of phospho-JAK3 but undetectable levels of phospho-JAK1 and -JAK2." (PMID 20149240, 2010). "JAK1, JAK2, and JAK3 immunoprecipitates were prepared from the lysates of Hodgkin's lymphoma HDLM-2 or L540 cells, where persistently-active JAK1 and JAK2 or JAK3 are expressed, respectively." (PMID 20149240, 2010).
Lung Injury (5 papers, 2021 to 2026). "A study suggested that IL-13 could activate the JAK1/STAT1 pathway to prevent neuronal death and restore brain functions after traumatic brain injury." (PMID 35757105, 2022).
oral cancer (5 papers, 2020 to 2026). "For instance, P. gingivalis promoted cell invasion and proliferation in an oral cancer mouse model via JAK1/STAT3 signaling pathway activation and EMT in tumor microenvironment (TME)." (PMID 40002861, 2025). "The JAK1/STAT3 signalling pathway inhibitor niclosamide also inhibited VM in oral cancer." (PMID 38459564, 2024). "In another study, F. nucleatum upregulated MMP1, MMP9, and IL-8 in oral cancer cell lines, and the infected cell lines showed overexpression of cell survival markers, such as MYC, JAK1 and STAT3, and EMT markers (ZEB1 and TGF-β)." (PMID 40002861, 2025). "Accordingly, we measured the expression of STAT3, JAK1, and MYC in three oral cancer cell lines (OQ01, HN, BHY) after polymicrobial infection with the combination of P. gingivalis, F. nucleatum, T. denticola, and T. forsythia by qRT-PCR." (PMID 33391626, 2020). "Moreover, phosphorylation of protein kinase C delta PKC-delta, Janus kinase 1 (JAK1), and Janus kinase 2 (JAK2), which are the upstream activators of STAT1 are also inhibited by EGCG in interferon gamma (IFNγ)-stimulated oral cancer cells." (PMID 32290543, 2020).
sarcoma (5 papers, 2019 to 2025). A usually aggressive malignant neoplasm of the soft tissue or bone. "There were the highest PD‐L1, PD‐L2 genetic alteration frequency in which amplification accounted for the majority in sarcoma tumour samples with the highest genetic amplification frequencies of JAK1 and BTG1." (PMID 38450981, 2024).
T-cell lymphoma (5 papers, 2015 to 2023). "For T-cell lymphoma six genes are found in cosmic (JAK1, PLCG1, FYN, ARID1A, EP300, and MAP3K1), and 13 are known oncogenes." (PMID 34570764, 2021). "Interestingly, an association between the JAK1 expression and the STAT3 activation has been reported in T-cell lymphomas." (PMID 30123428, 2018).
uveitis (5 papers, 2016 to 2026). An inflammatory process affecting a part of or the entire uvea. "Filgotinib (Jyseleca; Galapagos NV, Mechelen, Belgium) a preferential JAK1 inhibitor, demonstrated efficacy in reducing the risk of uveitis flare by week six of therapy in a Phase II randomised, placebo-controlled trial." (PMID 41198980, 2026). "Apart from JAK3, another gene named as JAK1 (ENSP00000343204) was also inferred to be a potential pathogenic uveitis-related gene by our method." (PMID 30349554, 2018). "Twenty-one months later, the patient was placed on the selective JAK1 inhibitor, upadacitinib 45 mg daily, per an agreement between her uveitis specialist and rheumatologist." (PMID 40689111, 2025). "Inflammatory cytokines, such as IL-6, which transduces cell signaling through the JAK/STAT pathway, and TNF, whose expression is reduced by inhibition of JAK1 and JAK2, are considered to be associated with the pathology of JIA-uveitis and ANA-positive uveitis." (PMID 34627340, 2021). "In addition, an association was found between SNPs (rs2780815, rs310241, rs3790532, rs310230, and rs310236) in JAK1 and Behçet disease (BD) as well as Vogt-Koyanagi-Harada (VKH) syndrome, two other common uveitis entities in China." (PMID 27965977, 2016).
acne (4 papers, 2023 to 2026). An inflammatory process of the sebaceous glands which is characterized by comedones, nodules, papules and/or pustules on the skin. "Previous research has demonstrated that JAK is overexpressed in common acne lesions, suggesting that combined JAK1 and JAK2 inhibitors could potentially be therapeutic for acne." (PMID 40860887, 2025). "Contrary to what has been said, there are reports that JAK1 and JAK3 have been proven to be overexpressed in acne lesions, so theoretically, inhibition of JAKs should alleviate acne." (PMID 41481132, 2026).
alopecia (4 papers, 2021 to 2025). Hair loss usually from the scalp. "The signal pathways associated with IL2-Rβ, JAK1, and STAT1 in CD8+ T cells are involved in alopecia." (PMID 39063064, 2024). "In CD8+ T cells, GE2000 and E40 downregulated alopecia-activating markers including IL2-Rβ, JAK1 (Janus kinase 1), and STAT1 (signal transducer and activator of transcription 1) under DT1 influence." (PMID 39063064, 2024). "Using hair follicle-specific JAK1/2 and STAT1 knockout mice, we expanded the spectrum of activity of the JAK inhibitors to HFSC-specific protection from chronic inflammation resulting in scarring alopecia." (PMID 39521937, 2024). "Additionally, they suppressed alopecia-related genes (NKG2DL, IL2-Rβ, JAK1, STAT1) in CD8+ T cells." (PMID 39063064, 2024).
autoimmune thyroid disease (4 papers, 2021 to 2025). Inflammatory disease of the thyroid gland due to autoimmune responses leading to lymphocytic infiltration of the gland. "Total glucosides of paeony (TGP) can regulate the expression of SOCS1 in rats with autoimmune thyroiditis, enhance the expression of JAK1, JAK2, STAT3, and STAT5, thereby affecting the JAK/STAT signaling pathway." (PMID 40584613, 2025).
Behçet’s disease (4 papers, 2016 to 2025). "Additionally, genetic factors may contribute to this regulation, as genetic variants in STAT3, STAT4, and JAK1 have been associated with an increased risk of ocular involvement in patients with Behçet’s disease." (PMID 40270958, 2025). "It is known that JAK1/STAT3 signaling pathway is activated in some systemic vasculitides (Behcet disease) through the activation of Th1/Th17-type cytokines such as IL-2, interferon (IFN-γ), IL-6, IL-17, and IL-23 but its role in KD is not well-understood." (PMID 33692975, 2021).
Cognitive impairment (4 papers, 2023 to 2025). Abnormal cognition is characterized by deficits in thinking, reasoning, or remembering. "Experimental validation results demonstrated that PN improves depressive mood and cognitive impairment in SD mice by inhibiting the over-activation of the JAK1/STAT3 pathway, reducing oxidative stress and inflammatory responses, and modulating neurotransmitters." (PMID 40076470, 2025).
dengue (4 papers, 2018 to 2024). "In addition, a genetic study from Brazil identified a strong association between a polymorphism in JAK1 and severe dengue and showed a different distribution of mutations by race consistent with the epidemiologic data." (PMID 30541456, 2018). "This will be the first trial of immunomodulation in dengue using biomarker-based enrichment for patient selection, and we hope that platforms to evaluate other host-directed therapeutics, such as the Janus kinase 1/2 inhibitor Baricitinib, will follow." (PMID 38536887, 2024).
depression (4 papers, 2022 to 2023). "The results showed that sodium valproate can improve the depression-like and cognitive dysfunction of rats after chronic restraint stress by activating the JAK1/STAT3 pathway and inhibiting the activation of inflammatory factors." (PMID 35148670, 2022). "Bai’s study showed that the levels of p-JAK1/JAK1 and p-STAT3/STAT3 were significantly decreased in the hippocampal tissue of the depression rats." (PMID 36686689, 2022). "Echinacoside ameliorates depression-like behavior in CUMS mice, possibly through enhancing BDNF-CREB pathway and inhibiting neuroinflammation via regulating microglia M1/M2 polarization and JAK1/STAT3 pathway." (PMID 36686689, 2022).
dermatomyositis (4 papers, 2020 to 2025). Dermatomyositis (DM) is a type of idiopathic inflammatory myopathy characterized by evocative skin lesions and symmetrical proximal muscle weakness. "Other small-molecule inhibitors include tofacitinib, a Janus kinase (JAK)-1/3 inhibitor, and ruxolitinib, a selective JAK-1/2 inhibitor, which suppress interleukin and interferon signaling in dermatomyositis." (PMID 33584696, 2020). "Ruxolitinib is a selective JAK1/2 inhibitor, and its application in treating adult-onset dermatomyositis(DM) has rarely been described." (PMID 40574830, 2025).
eczema (4 papers, 2019 to 2026). "Both MTMZM and Pevisone can alleviate the symptoms of eczema, promote the recovery of skin lesions, reduce inflammation factors, and reduce the level of proteins associated with P38/NF-κB and JAK1/STAT6 pathways." (PMID 40933470, 2025). "Ultimately, combination therapy with the JAK1 inhibitor upadacitinib and the PDE4 inhibitor apremilast achieved satisfactory control of both the paradoxical eczema and the underlying psoriatic lesions." (PMID 42079624, 2026). "This study aims to explore the therapeutic effect of MTMZM on rats with eczema and its influence on P38/NF-κB and JAK1/STAT6 pathway." (PMID 40933470, 2025).
esophageal cancer (4 papers, 2020 to 2023). A primary or metastatic malignant neoplasm involving the esophagus. "However, the constitutive activation of this pathway was found to promote the aggressiveness in breast and esophageal cancer, and the elevated phosphorylation levels of JAK1 and STAT3 were linked with the dismal prognosis." (PMID 38095644, 2023). "To uncover the mechanism through which genistein affects cyclical distribution and apoptosis in esophageal cancer cells, we tested the expression levels and phosphorylation levels of JAK1, JAK2, STAT1 and STAT3 in Eca-109 cells." (PMID 32276266, 2020).
gastritis (4 papers, 2020 to 2025). Inflammation of the stomach. "Empirical evidence suggests that Combined Formulas for Gastritis and DangguiShaoyao powder can effectively inhibit JAK1/STAT3 signaling pathways." (PMID 38698812, 2024). "In addition, the authors confirm that JAK1 and STAT3 are target genes of miR-1006b-5p and that the JAK1/STAT3 pathway plays a part in gastric inflammation (gastritis establishment) and carcinogenesis." (PMID 32260540, 2020). "In addition, PTGS2, TRL4, MMP9, JAK1, EGFR, CYP2C19, and PTGS1 were identified as crucial anti-gastritis target genes in C. cassia." (PMID 35336597, 2022).
hepatitis C (4 papers, 2017 to 2020). "Suppression and impairment of anti-viral activity of interferon α (IFNα) has been shown in hepatitis C infection through inhibition of Jak1/Tyk2/STAT1 phosphorylation and upregulation of PP2A dependent upon NS5A protein." (PMID 29447178, 2018).
metastatic tumors (4 papers, 2022 to 2024). "The study identified high frequencies of mutations in genes such as KMT2D (46.4% in primary and 33.3% in metastatic tumors) and JAK1 (31.9% in primary and 28.3% in metastatic tumors)." (PMID 39590142, 2024). "To demonstrate the effect of CYB5A on JAK1 inhibitor function, we applied Ruxolitinib in metastatic tumors with high CYB5A expression and found that it slowed disease progression and prolonged survival in mice." (PMID 35851063, 2022). "This suggests that, possibly, metastatic tumors in patients with high CYB5A expression exhibit more sensitivity to JAK1 inhibitors." (PMID 35851063, 2022). "For metastatic tumors from GENIE, a total of sixteen candidate genes had significantly higher SNV frequencies in MMR-d tumors, of which six genes (KMT2D (33.3%), JAK1 (28.3%), FAT1 (21.7%), ERBB4 (20.0%), KMT2A (20.0%), and MGA (20.0%)) had a SNV frequency ≥ 20% in MMR-d tumors." (PMID 36675550, 2023). "Single nucleotide variant (SNV) frequencies of 34 candidate genes (including KMT2D (46.4%), ZFHX3 (33.3%), JAK1 (31.9%), and RNF43 (27.5%)) and 16 candidate genes (including KMT2D (33.3%) and JAK1 (28.3%)) were higher in MMR-d primary tumors and MMR-d metastatic tumors, respectively." (PMID 36675550, 2023). "TempO-Seq analysis showed upregulation of innate immune response and IRF pathway genes (IRF1, IRF7, IFNAR2, JAK1, STAT1), yet no reduction was observed in the metastatic tumors." (PMID 38516270, 2024).
Nephropathy (4 papers, 2022 to 2025). A nonspecific term referring to disease or damage of the kidneys. "Moreover, the expression of JAK1, AKT1, and NF-κB was significantly increased in the model group, and there was low expression in the Nephropathy 1st group." (PMID 36339588, 2022). "To highlight the value of UM30-OSN in modeling APOL1-mediated kidney disease with an APOL1 (G1/G0) genotype, we examined how Interferon-γ (IFN-γ) affects UM30-OSN–derived podocytes and assessed whether the JAK1/JAK2 inhibitor Baricitinib can counteract IFN-γ–induced cellular responses." (PMID 41225540, 2025).
neuroblastoma (4 papers, 2013 to 2021). Neuroblastoma (NB) is the most common solid, extracranial childhood tumor. "A Previous study has shown that the JAK1/2 inhibitor, AZD1480, could abate neuroblastoma tumor cells growth and extend survivals, suggesting that S1 patients not only maintained better survivals with neuroblastoma, but also might potentially respond to drugs such as AZD1480 to recover." (PMID 34336652, 2021).